SMO (smoothened, frizzled class receptor)
Diseases named in the same sentence as SMO in open-access papers (continued):
Sharing a sentence is not in itself a finding about the gene and the disease.
cancer (continued). "The authors show also a positive correlation between the expression of MEP50/PRMT5 and that of GLI1 target genes in several HH-dependent cancers, and demonstrate that targeting of MEP50/PRMT5 complex may synergize with SMO inhibitors in suppressing cancer cell proliferation and invasion." (PMID 31244888, 2019). "Since non-canonical signaling may result in oncogenic expression of GLI1, inhibiting upstream molecules like SMO may not be useful for cancer therapy." (PMID 31085420, 2019). "Mechanistically, GLI1 is phosphorylated and activated in a SMO-independent manner by MAPK-ERK1/2 signaling, that can be induced by KRAS or through stimulation of Neuropilin 2 receptor by its ligand VEGFA, secreted by cancer cells in an autocrine loop or by stromal cells in a paracrine manner." (PMID 31244888, 2019). "To date, two SMO inhibitors (sonidegib and vismodegib) have received US Food and Drug Administration (FDA) approval for treating BCC, while many clinical trials are being conducted to evaluate the efficacy of this exciting class of targeted therapies in a variety of cancers." (PMID 30759860, 2019). "Thus, a more effective therapeutic approach to fight cancers harboring non-canonical HH pathway activation would be to inhibit the GLI rather than SMO." (PMID 31244888, 2019). "Indeed, amounting evidence indicate that ligand-independent hedgehog signaling, also named non-canonical hedgehog signaling, not sensitive to SMO inhibitors plays an essential role in cancer." (PMID 28872614, 2017). "Thus, given the modest activity of the FDA-approved SMO inhibitors against xenografts of human T-ALL and the known issue of emergence of resistance to these drugs in other cancer clinical trials, it will be imperative to determine which signaling pathways alter sensitivity to HH pathway inhibitors." (PMID 28872614, 2017). "In light of these findings we hypothesized that targeting DYRK1B may represent a novel strategy to inhibit oncogenic GLI1 activity in cancer cells with non-canonical, SMO-independent GLI1 activation." (PMID 26784250, 2016). "Thus, the “non-canonical” activation of the Hh signaling pathway in cancer leads to the transcription of GLI target genes in a SMO-independent manner via alternative signaling pathways." (PMID 26843616, 2016). "These oncogenic properties together with the capacity of GLI1 to integrate and relay common SMO-independent cancer-promoting cues such as receptor-tyrosine kinase pathways, PI3K and MAP kinase signaling render GLI1 an attractive molecular target for cancer therapy." (PMID 26784250, 2016). "Identification of these alternative pathways clearly showed that in order to suppress the hedgehog pathway activity completely in these three types of cancer cell lines, only the SMO inhibition would not be effective, as there were other molecules/proteins which were still activating the pathway." (PMID 23935937, 2013). "We observed that although the activation pathways (broken red arrows)from SMO to GLI1 and GLI2 via STK36 protein were blocked by the effect of SMO inhibitor in each cancer scenario, HFU could also activate GLI1 and GLI2 in each cancer scenario (solid green arrows)." (PMID 23935937, 2013). "In addition to the canonical pathway of activation, GLI transcription factors could be activated via noncanonical mechanisms (which bypass the HH ligand–PTCH/SMO axis), mostly in cancer cells, as we shall discuss in Section 3.2." (PMID 36769284, 2023). "Arguably, these models provide a holistic view of the paradigms of hedgehog signaling networks involving GLI regulation at the SMO level or beyond and may be more relevant to current therapeutic strategies involving the development of SMO and GLI inhibitors for treating Hh-dependent cancers." (PMID 34572373, 2021). "Therefore, SMO-dependent noncanonical HH signaling could affect cellular migration and contribute to the cancer progression." (PMID 32962123, 2020).
cancer (continued). "However, the GLI1 inhibitor blocked the Hh pathway more effectively than the SMO inhibitor, likely because cancer cells exhibit “non-canonical” activation of the Hh pathway, which is caused by alternative signaling pathways (ErbB receptors, NF-κB, Wnt, and Notch)." (PMID 26843616, 2016). "Thus, inhibition of Hh signaling at the level of GLI transcription factors, rather than the level of SMO, might be a more effective way to combat cancer." (PMID 26343727, 2015). "A wealth of studies have also reported non-canonical mechanisms of GLI activation in cancer, which are triggered independently of the upstream PTCH/SMO signalling." (PMID 34681917, 2021). "Many studies have also reported non-canonical mechanisms of GLI activation in cancer, which may occur independently of upstream PTCH/SMO signaling." (PMID 39998753, 2025). "There have also been reports of non-canonical Gli activation pathways in cancer, which may take place without the involvement of upstream PTCH/SMO signaling." (PMID 37240209, 2023). "Besides the canonical, ligand-induced HH signaling, SMO-independent, non-canonical ways to activate GLI have been reported in many cancers." (PMID 35908024, 2022). "Several studies have also reported non-canonical mechanisms of GLI activation in cancer, which may occur independent of upstream PTCH/SMO signaling." (PMID 33958721, 2021). "Interestingly, the HH-GLI pathway is involved in intense cross-talk with numerous signalling pathways that promote cancer progression, activating GLI in absence of the canonical PTCH/SMO pathway." (PMID 32814794, 2020).
hematologic malignancies (6 papers, 2014 to 2022). "Clinical-grade SMO inhibitors are currently under clinical trials for both solid tumors and hematologic malignancies." (PMID 25861282, 2015). "List of clinical trials of SMO inhibitors in hematological malignancies (from clinical trials.gov)." (PMID 36091167, 2022). "These inhibitors, as well as the SMO inhibitors vismodegib (first in class) and BMS-833923, are being investigated in other hematologic malignancies, including ALL, AML/MDS, CML, and MM." (PMID 24598114, 2014).
CNS tumor (3 papers, 2024 to 2025). "Currently, drugs that target SHH signalling pathways in CNS tumours can be categorised into SMO inhibitors, GLI inhibitors and SHH inhibitors." (PMID 39568072, 2024). "The most commonly overexpressed genes in CNS tumors included TOP2A (67%), BIRC5 (59%), CDK4 (50%), BRIP1 (49%), NOTCH1 (41%), SMO (39%), and TP73 (39%)." (PMID 38347552, 2024). "Additionally, targeting SMO, GLI, and SHH signalling in non-CNS tumours suggests potential applications in CNS tumours, underscoring the need for further research." (PMID 39568072, 2024).
neoplasms of the nervous system (2 papers, 2019 to 2025). "First, BDNF, WDPCP, APC and SMO are associated with neoplasms of the nervous system, especially the pituitary gland (group BN)." (PMID 40831500, 2025).
infection (1 paper, 2022). The state of being infected such as from the introduction of a foreign agent such as serum, vaccine, antigenic substance or organism. "In addition, we tested cytoplasmic fractions of SMO during E. chaffeensis-infection and found induced SMO protein expression during infection." (PMID 35576232, 2022).
neurodegenerative disease (1 paper, 2024). A disorder of the central nervous system characterized by gradual and progressive loss of neural tissue and neurologic function. "It has been found that the deregulation of the SMO-SHH signaling pathway can cause neurodegenerative diseases such as PD, nerve damage, neuronal excitotoxicity, increased oxidative stress, neuroinflammation, and apoptosis." (PMID 39364348, 2024). "In SHH pathway, the deregulation of SMO-SHH signaling pathway can cause neurodegenerative diseases such as PD, and the activation of the SMO-SHH-GLI pathway has neuroprotective, anti-inflammatory and antioxidant properties." (PMID 39364348, 2024).
neurological diseases (1 paper, 2024). "SMO, a key G protein-coupled receptor (GPCR) in the Sonic Hedgehog (SHH) pathway, promotes neuroprotection and recovery in neurological diseases." (PMID 39571157, 2024).
SMO also shares sentences with these, for which no sentence is quoted: small cell lung carcinoma (3 papers); acute lymphoblastic leukemia (2); acute promyelocytic leukemia (2); breast invasive carcinoma (2); cutaneous melanoma (2); depression (2); hypothalamic hamartoma (2); intraventricular meningioma (2); myelodysplastic syndrome (2); myeloproliferative disease (2); Psammomatous Meningioma (2); renal fibrosis (2); Secretory Meningioma (2); squamous cell carcinoma (2); adenomatoid odontogenic tumor (1); allergic disease (1); atypical teratoid rhabdoid tumor (1); autism (1); autosomal dominant polycystic kidney disease (1); autosomal-dominant inherited disorder (1); benign mesothelioma (1); biliary tract cancer (1); capillary malformation (1); carcinoids (1); central neurocytoma (1); cervical squamous cell carcinoma (1); colorectal adenoma (1); congenital malformation syndrome (1); convulsion (1); craniopharyngioma (1).
A further 45 diseases each share a sentence with SMO in 1 paper.